IL12RB1 (interleukin 12 receptor subunit beta 1)
Diseases named in the same sentence as IL12RB1 in open-access papers (continued):
Sharing a sentence is not in itself a finding about the gene and the disease.
malaria (3 papers, 2010 to 2019). Malaria is a serious and sometimes fatal disease caused by a parasite that commonly infects a certain type of mosquito which feeds on humans. "Because the single SNP regression analysis demonstrated that multiple sites within IL12A and IL12RB1 genes are significantly associated with protection from severe malaria anaemia, analysis of LD in these two genes was performed respectively." (PMID 20350312, 2010). "The results from this study also suggest that the effects of IL12A and IL12RB1 on malaria disease outcomes most likely result from the long evolutionary history of P falciparum parasite within the human population." (PMID 20350312, 2010). "IL12RB1 and TNF haplotypes were associated with malaria susceptibility." (PMID 23217179, 2012). "In a gene-based association study with 18 candidate genes for malaria susceptibility using 33 SNPs as genetic markers, this study demonstrated that IL1B, IL4R, IL12RB1 and TNF genes were associated with susceptibility to P. vivax malaria in a population of Pará state, Brazil." (PMID 23217179, 2012). "The IL1B gene -5839C > T and IL4R 1902A > G polymorphisms and IL12RB1 -1094A/-641C and TNF -1031 T/-863A/-857 T/-308 G/-238 G haplotypes were associated with malaria susceptibility after population structure correction (p = 0.04, p = 0.02, p = 0.01 and p = 0.01, respectively)." (PMID 23217179, 2012). "Currently, whether the polymorphisms in IL12A and IL12RB1 observed in this study influence the level and expression of IL12, IL12 receptor and IL23 in vitro in relation to severity of malaria anaemia have being examined in Kenyan children." (PMID 20350312, 2010). "This study has shown strong associations between polymorphisms in the genes of IL12A and IL12RB1 and protection from SMA in Kenyan children, suggesting that human genetic variants of IL12 related genes may significantly contribute to the development of anaemia in malaria patients." (PMID 20350312, 2010).
mycobacterial infections (3 papers, 2018 to 2024). "A large series of IL12Rβ1 patients reported only 6 patients with isolated Mycobacterium tuberculosis infections, and in this group, mycobacterial infections caused by BCG and EM are more common." (PMID 38535546, 2024). "Patients 1 and 2 are the first reports of children with Mycobacterium infection due to IL-12Rβ1 deficiency in Iran." (PMID 29256176, 2018). "Our findings suggest that the presence of IL-12Rβ1 deficiency should be determined in children with mycobacterial infections at least in countries with a high prevalence of parental consanguinity and in areas endemic for TB like Iran." (PMID 29256176, 2018). "Salmonella infections remain undiagnosed in most of the IL12Rβ1 patients due to the accompanying mycobacterial infections and antibiotics used for treatment." (PMID 38535546, 2024).
myocarditis (3 papers, 2004 to 2022). Myocarditis is a condition that is characterized by inflammation of the heart muscle (myocardium). "Similarly, in the experimental autoimmune myocarditis model, IL-12Rβ1 signaling and increased IL-1β levels are associated with the development of myocarditis." (PMID 15550215, 2004). "Single-case or small cohort studies identified Interleukin 12 receptor subunit beta 1 (IL12RB1) variants and the TLR3 p.Pro554Ser variant as genetic susceptibility factors for myocarditis." (PMID 35877578, 2022). "Recently, we demonstrated that CB3 infection increases IL-1β and IL-18 levels in the heart during acute myocarditis through IL-12Rβ1 and TLR4 signaling." (PMID 15550215, 2004). "They found that the severity of myocarditis, degree of viral replication, and levels of IL-1β/IL-18 expression were significantly reduced in TLR4-deficient mice and that TLR4 as well as IL-12Rβ1 aggravated CVB3 infection and myocarditis but IFN-γ inhibited viral replication." (PMID 29854842, 2018). "TLR4 and IL-12Rβ1 might share common downstream pathways that directly affected IL-1β and IL-18 production, and IL-1beta and IL-18 played an important part in the pathogenesis of CVB3-induced myocarditis." (PMID 29854842, 2018).
asthma (2 papers, 2014 to 2018). "In addition, IL-27 is a member of the IL-6/IL-12 family of cytokines, and rare variants in IL12RB1 have been previously implicated in asthma, suggesting that this family of cytokines and receptors should be the target of additional studies." (PMID 25116239, 2014).
colitis (2 papers, 2022 to 2024). Inflammation of the colon. "Further studies are required to identify the exact contribution of IL-12Rβ1 and IL-12Rβ2 in mediating the proinflammatory functions of IL-21/IL-21R signaling during colitis." (PMID 38498592, 2024). "Specifically, it was found that the expression of Ifng, Il12rb1, and Il12rb2 was impaired in colonic CD4+ T cells of Il21r−/− mice during C. rodentium–induced colitis." (PMID 38498592, 2024). "It was hypothesized that IL-21 would be required for the optimal expression of IL-12Rβ2, but not IL-12Rβ1, in CD4+ T cells, thereby regulating a TH1-biased immune profile following colon inflammation." (PMID 38498592, 2024).
fibrosarcoma (2 papers, 2022 to 2023). A malignant mesenchymal fibroblastic neoplasm affecting the soft tissue and bone. "We transfected JAK2-deficient γ2A-fibrosarcoma cells expressing IL-23R and IL-12Rβ1 with various amounts of JAK2-encoding constructs and assessed their response to IL-23." (PMID 37875108, 2023). "Like P1104A, all the missense proteins resulted in impaired responses to IL-23 in TYK2-deficient fibrosarcoma (U1A) cells stably expressing IL-12Rβ1 and IL-23R." (PMID 36094518, 2022).
multiple sclerosis (2 papers, 2023). A progressive autoimmune disorder affecting the central nervous system resulting in demyelination. "A recent study linked p40 monomer to the attenuation of autoimmune signaling in multiple sclerosis (MS) via suppression of IL-12Rβ1 internalization in a murine model (EAE) as well as in human patients." (PMID 36972230, 2023).
oral candidiasis (2 papers, 2018 to 2022). Infection of the mucosal lining of the mouth with the fungus Candida albicans. "In conclusion, in this study, we show that the treatment of oral candidiasis with polyvalent human IgG mouthwash helped eliminate the infection in two patients with an IL-12Rβ1 deficiency and a STAT1 GOF mutation." (PMID 30627128, 2018). "Two girls with primary immunodeficiency affecting IFN-γ and IL-17 production, and with mutations in their IL12RB1 and STAT1 genes, were treated for oral candidiasis with IVIG mouthwash." (PMID 36713426, 2022).
Primary Immunodeficiency (2 papers, 2017 to 2022). "Interleukin 12 receptor beta 1 (IL12Rβ1) deficiency is a primary immunodeficiency resulting mainly in susceptibility to opportunistic infection by non-tuberculous, environmental mycobacteria and severe infection caused by Salmonella spp." (PMID 28804486, 2017).
sarcoidosis (2 papers, 2014 to 2022). Sarcoidosis is a multisystemic disorder of unknown cause characterized by the formation of immune granulomas in involved organs. "IL-12Rβ1 and IL-12Rβ2 levels are elevated in sarcoidosis patients." (PMID 25386143, 2014). "The corresponding IL-12 receptor chain IL-12Rβ1 is equally over-expressed in peripheral blood and BAL of sarcoidosis patients." (PMID 25386143, 2014).
vasculitis (2 papers, 2021 to 2022). "Vasculitis should be considered in the differential diagnosis in patients with IL12RB1 deficiency presenting with a cutaneous eruption." (PMID 35198320, 2022). "The most prevalent genetic defect in MSMD patients with vasculitis was IL-12RB1 (16 of 18, 88.9%)." (PMID 34389021, 2021).
AIDS (1 paper, 2015). A syndrome resulting from the acquired deficiency of cellular immunity caused by the human immunodeficiency virus (HIV). "IL-18, CCL2, TRAF6 and IL-12Rβ1 were upregulated in both AIDS and IBD patients compared to controls." (PMID 26475133, 2015).
autoimmune lymphoproliferative syndrome (1 paper, 2022). Autoimmune lymphoproliferative syndrome (ALPS) is a rare, inherited disorder characterized by non-malignant lymphoproliferation, multilineage cytopenias, and a lifelong increased risk of Hodgkin's and non-Hodgkin's lymphoma. "A male patient presented with autoimmune lymphoproliferative syndrome phenotype and had 20% CD4-CD8-TCRαβ + cells, WES revealed homozygous pathogenic variant in IL12RB1." (PMID 35482138, 2022).
autoimmune polyendocrine syndrome type 1 (1 paper, 2016). Autoimmune polyendocrinopathy type 1, or APECED syndrome, is a genetic disease that manifests in childhood or early adolescence with a combination of chronic mucocutaneous candidiasis, hypoparathyroidism and autoimmune adrenal failure. "CMC in such patients may be part of a complex clinical phenotype exemplified by a dominant-negative STAT3 deficiency, interleukin (IL)-12Rβ1 and IL-12p40 deficiencies, and autoimmune polyendocrine syndrome type 1 (APS-1)." (PMID 27703456, 2016).
chronic granulomatous disease (1 paper, 2025). Chronic granulomatous disease (CGD) is a rare primary immunodeficiency, mainly affecting phagocytes, which is characterized by an increased susceptibility to severe and recurrent bacterial and fungal infections, along with the development of granulomas. "Six cases (37.5%) had chronic granulomatous disease (CGD) due to CYBB gene mutations, 2 cases (12.5%) had Mendelian susceptibility to mycobacterial disease (MSMD) due to IL12RB1 mutations, and 1 case (6.25%) had a FADD gene mutation." (PMID 40470261, 2025).
combined immunodeficiency (1 paper, 2019). A broad classification of inherited disorders presenting at birth that affect both the cell-mediated and humoral aspects of the immune response. "Underlying diagnoses were IL12RB1 deficiency, NFKB1 haploinsufficiency, IFNGR1 deficiency, GATA2 haploinsufficiency, Kabuki syndrome, NEMO deficiency, and undefined combined immunodeficiency (CID)." (PMID 30984189, 2019).
cryptococcosis (1 paper, 2018). An acute or chronic, localized or disseminated infection by Cryptococcus neoformans. "The IL12RB1 gene mutation has been reported in pediatric patients with cryptococcal osteomyelitis or disseminated cryptococcosis." (PMID 29596420, 2018).
epilepsy (1 paper, 2020). A brain disorder characterized by episodes of abnormally increased neuronal discharge resulting in transient episodes of sensory or motor neurological dysfunction, or psychic dysfunction. "Mir187 (paired with the Interleukin 12 Receptor Subunit Beta Il12rb1) is associated with the regulation of the potassium channel KCNK10/TREK-2 in a rat epilepsy model." (PMID 32093602, 2020).
glioma (1 paper, 2025). A benign or malignant brain and spinal cord tumor that arises from glial cells (astrocytes, oligodendrocytes, ependymal cells). "We confirmed that the expression profiles of relevant IL-12R genes (Il12rb1, Il12rb2, and Stat4) are comparable between human gliomas and the murine GB cell lines (CT-2A, GL261, and 005), supporting the utility of these mouse models for studying IL-12-mediated mechanisms in GB." (PMID 40842154, 2025).
head and neck cancer (1 paper, 2020). A primary or metastatic malignant neoplasm affecting the head and neck. "Previous studies have found associations of IL12RB1 and IL12RB2 gene-SNPs with cervical, vulvar and head and neck cancers." (PMID 32973967, 2020).
Hemophagocytic Lymphohistiocytosis (1 paper, 2023). "In this report, we describe a case of a previously healthy infant who was found to have IL12Rβ1 deficiency after she presented with hemophagocytic lymphohistiocytosis (HLH) secondary to severe Salmonella enterica sepsis." (PMID 37588305, 2023).
hepatic autoimmunity (1 paper, 2023). "The presence of significant hepatic autoantibodies in IL-12Rβ1–deficient patients suggests that IL-12Rβ1 signaling is closely related to hepatic autoimmunity." (PMID 37457696, 2023).
leptospirosis (1 paper, 2014). A contagious bacterial infection caused by spirochetes of the genus Leptospira. "For IL12RB1, our data demonstrates that in heterozygosity, the + 1196CG genotype has an increased risk in leptospirosis cases (p = 0.003), which contrast with the + 1196GG genotype that confers a protective effect (p = 0.003)." (PMID 25255143, 2014). "Nevertheless, the mechanism by which IL1β and IL12RB1 mediates protection against human leptospirosis is unknown." (PMID 25255143, 2014). "Results showed that genotypes -511GG (OR = 1.6, 95% CI 1.01–2.56, p = 0.04) in IL1β, +1196CG (OR = 2.0, 95% CI 1.26–3.27, p = 0.003) in IL12RB1, -292TA (OR = 1.8, 95% CI 1.06–2.1, p = 0.03) and +3415CG (OR = 1.8, 95% CI 1.08–3.08, p = 0.02), both in CISH, have increased risk to leptospirosis." (PMID 25255143, 2014).
measles (1 paper, 2021). A highly contagious viral infection caused by the measles virus. "For example, HLA class I and HLA class II genotypes and SNPs in cytokine/cytokine receptor genes (IL12B, IL12RB1, IL2, IL10) and the cell surface measles virus receptor the CD46 gene, have been reported to affect measles vaccine-induced immunity." (PMID 34683414, 2021).
melanoma (1 paper, 2020). A malignant, usually aggressive tumor composed of atypical, neoplastic melanocytes. "To explore the generalizability of these results, we also found that the expression of IL12RB2:IL12RB1 is similarly skewed in human melanoma based on transcriptional profiles of melanoma cells and tumor-infiltrating lymphocytes." (PMID 32450888, 2020).
nocardiosis (1 paper, 2022). Nocardiosis is a local (skin, lung, brain) or disseminated (whole body) acute, subacute, or chronic bacterial infection. "In addition, one patient had nocardiosis and infections caused by Enterobacteriaceae, as also reported in patients with IL-12Rβ1 or IL-12p40 deficiencies." (PMID 36094518, 2022).
oropharyngeal cancer (1 paper, 2023). Carcinoma, predominantly squamous cell, arising from the epithelial cells of the oropharynx. "Most of the oral and oropharyngeal cancer samples were unmethylated in almost all the investigated gene promoters: EDARADD, GBP4, HAVCR2, HLA DPB1, IL12RB1, MARCO, and SIGLEC12." (PMID 37175405, 2023).
prostate carcinoma (1 paper, 2022). A carcinoma that arises from epithelial cells of the prostate gland. "Accordingly, we have also seen that that p40 neutralization by p40 mAb stimulates the internalization of IL-12Rβ1 via caveolin to cause the death of prostate cancer cells via the IL-12–IFN-γ pathway." (PMID 35053375, 2022).
prostate tumors (1 paper, 2010). "These in vitro findings are further corroborated by our ex vivo data showing the expression IL-12Rβ1 and CD69 on iNKT cells in TRAMP prostate tumors." (PMID 20593019, 2010).
schizophrenia (1 paper, 2016). A major psychotic disorder characterized by abnormalities in the perception or expression of reality. "STRING analysis highlighted first-order protein interactions among IL12RB1 and IL12B, IL1B, IL6, and IL12A, all of which have previously been associated with schizophrenia." (PMID 27746755, 2016).
severe acute respiratory syndrome (1 paper, 2008). A viral respiratory infection caused by the SARS coronavirus. "We examined whether polymorphisms of interleukin (IL)-12 receptor B1 (IL-12RB1) affect the susceptibility to and outcome of severe acute respiratory syndrome (SARS)." (PMID 18478121, 2008).
Sjögren’s Syndrome (1 paper, 2017). "Here, we present the case of a 50-year-old male with IL12Rβ1-deficiency, who presented with fever episodes and sicca syndrome 18 months after starting of an antimycobacterial therapy due to the diagnosis of a disseminated infection with Bacillus Calmette–Guérin (BCG)." (PMID 28804486, 2017).
staphylococcal infection (1 paper, 2011). An infection caused by Staphylococcus. "Previous studies have shown that default of Il12rb1 gene expression is associated with susceptibility towards Mycobacteria and malarial infections, but until now, predisposition to staphylococcal infections has not been reported in relation with this default." (PMID 21857913, 2011).
uveitis (1 paper, 2014). An inflammatory process affecting a part of or the entire uvea. "Given the fact that these related genes (IL-12B, IL-12Rβ1 and IL-12Rβ2) play an important role in Th1 and Th17 related immune responses, we wanted to verify the potential evidence of an association of polymorphisms in these genes with uveitis." (PMID 24859272, 2014).
visceral leishmaniasis (1 paper, 2011). A severe form of leishmaniasis characterized by irregular bouts of fever, substantial weight loss, swelling of the spleen and liver, and anemia (which may be serious). "Another IL-12Rβ1-deficient patient with visceral leishmaniasis has previously been described." (PMID 21533230, 2011).
tumor (39 papers, 2009 to 2025). "Given that CD8POS T cells at the tumor site express 4–1BB, IL-12Rβ1/2, and tumor-specific Ags, their activation is likely limited by the scarcity or immunosuppressed state of Ccr7POS DCs." (PMID 40842154, 2025). "For the first time, this study proposes that GSDME achieves its anti-tumor effect by regulating the interaction of IL-12RB1-IL-12, which has been demonstrated through recovery experiments." (PMID 38169676, 2024). "Further, the expression of this miRNA was negatively correlated with IL-12Rβ1 expression, which led to increased production of IL-23 and tumor development." (PMID 39376808, 2024). "To address dose-limiting toxicity, we treated tumor-bearing mice with variants of IL-2 and IL-12 that were skewed toward T cells expressing CD25 and interleukin 12 receptor subunit beta 1 (Il12rb1), respectively." (PMID 37669107, 2023). "Therefore, it is likely that p40 mAb is also increasing the level of IFNγ in TNBC tumor of PDX mice via stimulation of IL-12Rβ1 internalization and upregulation of the IL-12 signaling pathways." (PMID 35053375, 2022). "In vitro pre‐activated T cells share main characteristics of antigen‐experienced T cells within the tumor microenvironment, such as upregulation of exhaustion markers PD‐1, TIM‐3, LAG‐3, and CTLA‐4 as well as enhanced IL‐12Rβ1 expression." (PMID 39981925, 2025). "In turn, signaling of the other interleukin included, IL-12RB1, leads to the synthesis of IFN-γ, which may have an antitumor role in the activation of effector T cells, which will destroy tumor cells." (PMID 39247183, 2024). "In addition, a low expression of IL12RB1, CD28, CCL3, and GZMA before treatment in the p16- tumour group conferred a higher rate of failure." (PMID 36835246, 2023). "This was not due to a direct effect of IL-12 on 4T1 tumour cells, since these cells did not express IL-12Rβ2 and IL-12Rβ1 and their in vitro growth was not affected by IL-12." (PMID 27982126, 2016). "Although we did not see any up-regulation of PD-1 or CD25 molecules on iNKT cells in TRAMP mice (data not shown), we consistently found strong up-regulation of IL-12Rβ1 on TIL-iNKT cells in tumor, but not from spleens, in both groups." (PMID 20593019, 2010). "Consistent with reduced Il12rb1 and Il12rb2 expression by primed, SIY-reactive CD8+ T cells in lung TdLNs, SIY-reactive CD8+ T cells from KP.SIY lung tumor–bearing mice bound significantly less IL12-MSA than SIY-reactive CD8+ T cells from flank tumor–bearing mice." (PMID 37669107, 2023).